MAMSTR (MEF2 activating motif and SAP domain containing transcriptional regulator)
Description:
Transcriptional coactivator. Stimulates the transcriptional activity of MEF2C. Stimulates MYOD1 activity in part via MEF2, resulting in an enhancement of skeletal muscle differentiation (By similarity).
Synonyms: MASTR; FLJ36070
Tractability: No criterion of Open Targets' tractability assessment is met for any kind of drug.
Gene: Protein-coding gene on chromosome 19 (48,711,737 to 48,719,725, reverse strand). Ensembl gene ENSG00000176909.
Subcellular location: Nucleus
Subcellular location (Human Protein Atlas): Nuclear speckles
Gene Ontology:
Molecular function: transcription coregulator activity
Biological process: regulation of transcription by RNA polymerase II
Cellular component: nucleus
Genetic constraint (gnomAD): Loss-of-function variants: 41 observed, 35.64 expected, observed/expected ratio (o/e) 1.15, 90% interval 0.89 to 1.49. The upper end of that interval is the gene's LOEUF score, 1.49, which puts it in group 6 of 6, group 1 being the genes least tolerant of losing a copy. Missense variants: 567 observed, 494.7 expected, observed/expected ratio (o/e) 1.15, 90% interval 1.07 to 1.23. Synonymous variants: 265 observed, 218.68 expected, observed/expected ratio (o/e) 1.21, 90% interval 1.1 to 1.34.
Homologues: Orthologues: macaque MAMSTR (97% identical), dog MAMSTR (82% identical), pig MAMSTR (80% identical), mouse Mamstr (76% identical), rat Mamstr (76% identical), chimpanzee MAMSTR (75% identical), guinea pig MAMSTR (71% identical), zebrafish mtdhb (15% identical), tropical clawed frog mtdh (15% identical), zebrafish mtdha (13% identical). Paralogues in human: MTDH (17% identical).
Diseases named in the same sentence as MAMSTR in open-access papers:
MAMSTR is named in the same sentence as 10 diseases in open-access papers, as found by Europe PMC text mining. Sharing a sentence is not in itself a finding about the gene and the disease. The quoted sentences say what the papers report.
asthma (1 paper, 2020). "Nine loci surpassed the genome-wide significance threshold, of which the FUT2/MAMSTR locus on chromosome 19, with the top SNP rs281379 (odds ratio (OR) = 1.18 (95% confidence interval (CI) = 1.11–1.25), Pdiscovery = 2.6 × 10−9), emerged as a novel locus associated with asthma." (PMID 33328473, 2020). "The novel FUT2/MAMSTR signal was replicated in the COPSAC birth cohorts (COPSAC2000 and COPSAC2010 combined), where there was evidence of an association between rs281379 and asthma before the age of 6 years (OR = 1.38 (95% CI = 1.09–1.75), Preplication 1 = 0.008)." (PMID 33328473, 2020).
Cirrhosis (1 paper, 2024). A chronic disorder of the liver in which liver tissue becomes scarred and is partially replaced by regenerative nodules and fibrotic tissue resulting in loss of liver function. "Other variants, such as those in HSD17B13 and MAMSTR, were found to have larger effects on cirrhosis compared with NAFLD, indicating a more dominant role in the progression to clinically advanced stages of chronic liver disease." (PMID 38632349, 2024). "Moreover, we found that the variants near HKDC1, HLA-DQB1 and MAMSTR likely influence cirrhosis via pathways distinct from those related to fatty liver disease." (PMID 38632349, 2024). "Of the 36 cirrhosis variants, we identified protein-altering variants in LD (r2 > 0.8) with the lead variant at 16 loci, including 3 splice variants in HSD17B13 (rs72613567, c.812+2dupT), MAMSTR (rs11666792, c.219+3G>A) and PYGB (rs2261790, c.1518+6T>C)." (PMID 38632349, 2024).
Hypertension (1 paper, 2025). The presence of chronic increased pressure in the systemic arterial system. "At the MAMSTR locus on chromosome 19, we also observed a shared genetic signal between the fatty acid trait and hypertension, with rs479486 identified as the most probable causal variant." (PMID 41024449, 2025).
schistosomiasis (1 paper, 2022). An infectious disease caused by parasitic trematodes of the genus Schistosoma that colonize human blood vessels and release eggs that can cause granulomatous reactions leading to acute (swimmer's itch or acute schistosomiasis syndrome) or chronic disease. "Our analyses also indicated that ITIH4, PMEPA1, and MAMSTR are potentially causal genes affecting the severity of schistosomiasis." (PMID 35493725, 2022). "This suggests that rs62132778 at the 19q13.33 locus might be a causal variant, and decreased gene expression of MAMSTR is related to increased risk of elevated levels of AST in schistosomiasis patients." (PMID 35493725, 2022).
MAMSTR also shares sentences with these, for which no sentence is quoted: Adenovirus Infection (1 paper); breast carcinoma (1); dental caries (1); fatty liver disease (1); periodontitis (1); psoriasis (1).